INS (insulin)
Diseases named in the same sentence as INS in open-access papers (continued):
Sharing a sentence is not in itself a finding about the gene and the disease.
Obesity (continued). "Moreover, at the same level of glycemia and insulin sensitivity, children with obesity have hyperresponsive β-cells compared to adults with obesity." (PMID 40831565, 2025). "Some studies indicate that HIIT might help reduce visceral fat and modestly enhance insulin sensitivity, which could contribute to better regulation of blood glucose levels in individuals with obesity." (PMID 40005372, 2025). "It is also known from previous studies that in obese states, NGF levels increase, and by binding to the receptor trkA could increase insulin secretion and generate hyperinsulinemia in obesity conditions." (PMID 39857710, 2025). "It has several beneficial effects: it improves cardiovascular health, improves insulin sensitivity and glucose tolerance, increases WAT mitochondrial activity, decreases the levels of circulating lipids, thus reducing the risk of obesity, T2DM, and other metabolic diseases." (PMID 40868241, 2025). "Surprisingly, gavage with R. torques improved high-fat diet (HFD)-induced obesity, glucose homeostasis, and insulin sensitivity in mice by increasing DCA levels, resulting in G-protein-coupled bile acid receptor (GPBAR1/TGR5) activation and elevation of white adipose tissue thermogenesis." (PMID 40084870, 2025). "Parameter k3, representing insulin secretion, showed an age-dependent increasing trend (p < 0.001 for each hypothesis test), indicating a progressive enhancement of insulin secretion during obesity progression under HFD feeding." (PMID 41433229, 2025). "Nevertheless, findings from non-pregnant studies indicate that succinate may act as a signalling metabolite influencing insulin secretion and obesity-induced inflammation, and expression of the succinate receptor SUCNR1 has been demonstrated in human placenta." (PMID 41202005, 2025). "Obesity may influence these three conditions through several interconnected mechanisms, including persistent inflammatory responses, oxidative damage, insulin resistance, and renin-angiotensin pathway stimulation." (PMID 41001669, 2025). "However, additional research is required to clarify the role of OVEO in modulating insulin sensitivity disrupted by saturated fatty acids, a phenomenon observed in obesity and other metabolic conditions." (PMID 40872520, 2025). "This supports the hypothesis that obesity-related chronic inflammation contributes to decreased insulin sensitivity." (PMID 41585812, 2025). "Indeed, obesity management has been revolutionised by GLP-1 agonists which stimulate insulin secretion, down-regulate appetite via central mechanisms and delay gastric emptying." (PMID 39653728, 2025). "Moreover, CB2R activity has been shown to reduce weight gain, relieve glucose tolerance, enhance insulin sensitivity, and attenuate inflammation by suppressing macrophage polarization in a mouse model of obesity." (PMID 40365131, 2025). "This potentially imbalanced relationship between insulin demand and insulin adequacy may easily decompensate in the presence of concomitant weight gain or obesity." (PMID 39611962, 2025). "Selenium affects obesity by enhancing insulin sensitivity and improving metabolism." (PMID 40182029, 2025). "Recent research indicates RV and quercetin, at varying doses, decrease inflammation by impacting SFRP4, a protein involved in obesity, diabetes, and pancreatic inflammation, thus highlighting a connection between obesity-driven inflammation and dysfunctional insulin response." (PMID 40732979, 2025). "It is interesting to speculate that insulin induction of BA production may be blocked selectively as an adaptive response to obesity." (PMID 41306439, 2025). "Indeed, in individuals with obesity and T2D, chronic low-grade inflammation, characterized by elevated IL-6 levels in various tissues, can contribute to reduced insulin sensitivity and impaired glucose metabolism." (PMID 41277875, 2025).
Obesity (continued). "Furthermore, ABSI provides a more accurate description of changes in circulating insulin and lipoproteins than traditional obesity indicators." (PMID 40007807, 2025). "By comparing groups fed distinct protein diets, we sought to determine how different dietary protein sources modulate obesity-related outcomes, insulin resistance, and pancreatic compensation, with a particular focus on adipose tissue remodeling and its impact on systemic metabolism." (PMID 41156477, 2025). "Collectively, these findings underscore the complexity of adipose-derived signals and their variable impact on local metabolic crosstalk, influencing lipid partitioning and insulin responsiveness within skeletal muscle and nearby connective tissues in obesity and T2DM." (PMID 41002965, 2025). "Obesity and/or insulin and glucose homeostasis are common PCOS comorbidities." (PMID 41048429, 2025). "On the other hand, obesity, which is a well-established risk factor for CRC, may promote tumorigenesis through chronic inflammation, insulin resistance, and altered adipokine regulation." (PMID 39940229, 2025). "Furthermore, previous studies have demonstrated that androgen excess can increase food intake and promote obesity by suppressing insulin and leptin signaling in the hypothalamus and upregulating the expression of pro-phagocytic genes." (PMID 40444232, 2025). "In obesity, there is increased infiltration of M1 macrophages in adipose tissue and a reduction in M2 cells, creating an inflammatory microenvironment that interferes with insulin signaling through inhibition of IRS-1 and reduced Akt phosphorylation." (PMID 41374016, 2025). "This hypothesis is supported by research in horses and humans, which show that obesity can lead to metabolic changes that in turn impair fertility In human males and females, glucose and insulin play critical roles in energy processing and metabolism." (PMID 40646763, 2025). "High insulin levels may also affect airway efferent parasympathetic nerves, as in previous studies showing that increased insulin correlates with airway hyperreactivity in rats with diet-induced obesity." (PMID 39782687, 2025). "The diet–obesity–brain axis spans behavioral intake, adiposity and insulin signaling." (PMID 41228565, 2025). "Beyond classical myokines, skeletal muscle secretes a variety of cytokines, chemokines, and metabolites that may indirectly influence local lipid handling and insulin sensitivity within muscle–adipose–connective tissue microenvironments in obesity and T2DM." (PMID 41002965, 2025). "While previous research on isolated TRE interventions in adults with obesity showed minimal changes in fasting glucose levels over 2-12 months, with significant improvements in insulin parameters primarily observed only in protocols implementing shorter eating windows scheduled earlier in the day16." (PMID 41309556, 2025). "Obesity also led to more frequent combined treatment with metformin and insulin." (PMID 40257685, 2025). "Factors such as chronic hyperglycaemia, obesity and dysregulated insulin signalling are involved in the development of T2D10 and may independently drive IPF pathogenesis." (PMID 39613458, 2025). "Pancreatic islets from offspring of mothers with obesity or high-nutrient diets exhibit lower insulin content, diminished Pdx1 expression in adult islets, and structural remodeling, including an increased presence of α -cells in the central regions of the islets." (PMID 41373994, 2025). "MDP-based postbiotics via NOD2 act as insulin sensitizers, as indicated by reduced adipose tissue inflammation and reduced glucose intolerance in mice with obesity without the alteration of gut microbiota and weight loss." (PMID 40592472, 2025). "Therefore, we propose that rutin is a bioactive component of RFE that inhibits adipogenic differentiation and lipogenesis while enhancing insulin sensitivity in obesity." (PMID 40076460, 2025).
Obesity (continued). "Previous studies in obese adults and normal mice have shown that consumption of high fat diet could affects GIPR and SREBF1 genes expression signalling that prevent obesity and improve insulin sensitivity." (PMID 40347281, 2025). "Furthermore, the GLP-1 secreting L cells or preproglucagon cells are present in the olfactory bulb (OB), and the GLP-1 receptor activation in the OB stimulates insulin release in response to sugar intake in normal and mice (male) with diet-induced obesity." (PMID 40592472, 2025). "Similarly, irisin intervention in HFD-induced obesity in mice induces white adipose tissue browning, improving blood glucose levels, insulin resistance, lipid metabolism, energy expenditure, and UCP1 expression." (PMID 41373506, 2025). "Previous studies have identified cochlear microvascular disease, dyslipidemia, oxidative stress imbalance, and alterations in insulin signaling as potential mechanisms through which diet, obesity, and metabolic diseases contribute to cochlear damage and hearing impairment." (PMID 40416381, 2025). "In obesity research, CRISPRa could be used to activate genes that promote fat breakdown, increase energy expenditure, or improve insulin sensitivity." (PMID 41150735, 2025). "These amino acids are known to influence insulin signaling and lipid metabolism, and their dysregulation may contribute to metabolic disturbances that characterize obesity and metabolic syndrome." (PMID 40575035, 2025). "Individuals with obesity often exhibit a predominance of type II (fast-twitch), glycolytic, and insulin-resistant fibers, which may contribute to systemic insulin resistance, despite having greater muscle mass." (PMID 41476919, 2025). "Obesity leads to CKD through multiple mechanisms: hemodynamic changes cause abnormal pressure within the kidneys, metabolic disorders trigger insulin and lipid metabolism disorders, and imbalances in adipocytokines, along with oxidative stress and inflammatory responses, exacerbate kidney damage." (PMID 40703164, 2025). "In a randomized controlled trial (RCT) involving adults with obesity and prediabetes, daily blueberry intake (equivalent to 300 g fresh blueberries, providing 668 mg of anthocyanins) over six weeks significantly improved insulin sensitivity." (PMID 40430501, 2025). "However, in obesity and insulin-resistant states, mitophagy becomes dysregulated, partly due to nutrient overload and chronic mTORC1 activation, which inhibit the ULK1 complex responsible for autophagy initiation." (PMID 40806527, 2025). "The identified DNA methylation patterns are related to key signalling pathways known to contribute to obesity pathogenesis and related functions such as insulin regulation, glucose metabolism, adipogenesis, body form, telomere maintenance, asthma and lung function." (PMID 40410506, 2025). "Also, obesity-induced hepatic IR is characterized by an inability for insulin to inhibit glucose output." (PMID 41020888, 2025). "Thus, TRZ, by regulating insulin sensitivity and obesity profile, reduces the detrimental effects of T2D and obesity on the pathogenesis of AD." (PMID 40498212, 2025). "CTI can mediate 12.7%–26.1% of obesity-related metabolic cognitive risk (MCR), and its mechanism may be related to inflammation-mediated vascular insulin resistance." (PMID 40809992, 2025). "Thus, Ctrp10-KO female mice represent a novel model of female obesity with largely preserved insulin sensitivity and metabolic health." (PMID 37961647, 2025). "Given its role in insulin signaling and glucose metabolism, hsa-miR-218-1-3p may serve as a biomarker for gender-specific metabolic differences in obesity, potentially guiding individualized treatment strategies." (PMID 40699679, 2025). "Obesity-induced lysosomal dysfunction impairs the autophagic degradation process, contributing to the accumulation of damaged organelles and toxic aggregates, exacerbating insulin resistance, lipotoxicity, and chronic inflammation." (PMID 40366502, 2025).
Obesity (continued). "Notably, inflammation-associated miRNAs (miR-27, miR-34a, miR-146a) reflected the transition from metabolically healthy to unhealthy obesity, while β-cell–related miRNAs (miR-30a, miR-126) indicated early impairment of insulin secretion." (PMID 41400625, 2025). "Simultaneously, through synergy with TRP receptors, SOCE machinery and mitochondrial membranes, these compounds bolster insulin sensitivity, ramp up energy expenditure and fine-tune lipid metabolism—underscoring their compelling therapeutic promise for obesity and metabolic syndrome." (PMID 40871490, 2025). "Despite causing obesity-induced hyperglycemia, the Cyp17a1 gene knockout did not affect insulin secretion or responsiveness." (PMID 41385510, 2025). "The data showed that as the CDAI increases in subjects with obesity carrying the TNF-α risk allele (A), a more pronounced downward trend in insulin levels was observed, compared to those with the GG genotype, supported by a statistically significant interaction." (PMID 40732969, 2025). "Pancreatic islets show increased macrophage density with obesity which mirrors findings in mouse models and may reflect macrophage functions in supporting homeostatic islet expansion to increase insulin output in obesity." (PMID 40909804, 2025). "Additionally, the accumulation of adipose tissue in obesity is thought to increase the production of various endogenous hormones such as sex steroids, insulin, and insulin-like growth factor-1." (PMID 41016748, 2025). "The liver is central to glucose homeostasis and triacylglycerol metabolism, developing steatosis in obesity, correlating with systemic insulin resistance in hepatic and muscle tissues, so it is therefore pivotal for elucidating metabolic dysregulation mechanisms." (PMID 41220714, 2025). "Similarly, we observed fibre type transition (slow‐to‐fast shift) along with impaired systemic and muscular insulin sensitivity in offspring exposed to maternal prepregnancy obesity." (PMID 40256914, 2025). "However, its lipogenic and insulin‐resistant effects in conditions like obesity and type 2 diabetes complicate its role." (PMID 39540705, 2025). "Several factors may explain this: men with obesity frequently have elevated serum levels of insulin, IGF-1, and leptin, with reduced adiponectin levels—all of which have been associated with prostate cancer in some studies." (PMID 40002302, 2025). "Mechanisms linking obesity to AD pathology include lipotoxicity, insulin resistance, adipokine signaling, inflammation, and immune cell fate shifts;3, 4, 5, 6 all of which are exacerbated in individuals with obesity and primarily contribute by the peripheral tissues." (PMID 41036709, 2025). "Thus, an HFHS diet was utilized and body weight was increased in response to increased caloric intake similar to other studies which have correlated HFHS consumption with increased body weight, BMI, obesity, peripheral tissue steatosis, and insulin resistance." (PMID 39910959, 2025). "The mechanisms by which this sustained SIK2 activity leads to diet-induced obesity might involve a coordinated alteration in insulin action, glucose uptake, and lipogenesis in the adipose tissue." (PMID 40384110, 2025). "Omentin levels are lower in obesity and metabolic syndrome; increasing omentin could improve insulin sensitivity and reduce inflammation." (PMID 40013194, 2025). "Of the multiple signaling pathways involved in obesity, the mitogen-activated protein kinase (MAPK) signaling members, extracellular signal-regulated kinase 1/2 (ERK1/2) and c-Jun N-terminal kinase (JNK), promote obesity by enhancing inflammation, insulin resistance, and adipogenesis." (PMID 40301996, 2025). "individuals with obesity if insulin secretion is insufficient." (PMID 39298040, 2025). "Insulin pump therapy (without automated insulin delivery) was associated with significantly higher rates of obesity in 2019, 2020, and 2022 compared with 2018 (P < 0.05 for each)." (PMID 39933614, 2025).
Obesity (continued). "Additionally, reductions in glycogen contentand increases in fasting blood glucose, fasting insulin level, HOMA-IR,and muscle triglyceride levels caused by obesity were amelioratedby the supplementation." (PMID 39754576, 2025). "The magnitude of this difference (5.84-fold) substantially exceeds the 4.43-fold odds ratio observed in the unmatched analysis, suggesting that age-matching enhanced the detection of true obesity-related metabolic dysfunction by reducing noise from age-related physiological insulin resistance." (PMID 41374006, 2025). "This demand further intensifies in INS-resistant states, pregnancy, or obesity." (PMID 40052150, 2025). "Excess glucose is transported in an insulin-dependent manner within the adipocyte to be transformed into fatty acids and glycerol 3-phosphate and form triglycerides with consequent expansion of adipose tissue and worsening of obesity." (PMID 38778593, 2025). "Obesity, hyperglycemia, and lipid metabolism disorders are common factors linking IR and hyperuricemia, as they promote purine metabolism, oxidative stress, and inflammation, leading to increased uric acid production and decreased insulin sensitivity." (PMID 40607233, 2025). "One proof‐of‐concept study demonstrated that a single‐dose oral FMT from healthy lean donors combined with a daily low‐fermentable fiber supplementation produced small but statistically significant improvements in insulin sensitivity in patients with severe obesity and metabolic syndrome." (PMID 40832705, 2025). "Alternatively, altered myokine secretion may result from muscle exposure to obesity-related metabolic factors, such as lipotoxicity and inflammation, which impair muscle insulin sensitivity." (PMID 40171198, 2025). "In the periphery, it promotes insulin secretion and has anti-obesity effects." (PMID 41309900, 2025). "Meta-inflammation in obesity disrupts insulin signaling through alterations in adipokine secretion and excessive free fatty acid (FFA) release, forming a pro-inflammatory microenvironment that impairs insulin sensitivity and reduces glucose uptake in peripheral tissues." (PMID 41235339, 2025). "Given their anti-inflammatory properties, anthocyanins are hypothesized to alleviate obesity-related disturbances in gut microbiota, insulin resistance, oxidative stress, and inflammation." (PMID 40703150, 2025). "Obesity is thought to influence both the onset and severity of psoriasis through mechanisms such as chronic low-grade inflammation, elevated levels of proinflammatory cytokines, insulin resistance, and broader metabolic disturbances." (PMID 41432618, 2025). "In contrast, the HIIT group exhibited a favorable hormonal profile characterized by reduced insulin and leptin levels (both typically elevated in obesity) and increased adiponectin concentrations, reflecting improved insulin sensitivity, leptin responsiveness, and adipose tissue function." (PMID 41367390, 2025). "At the molecular level, obesity is characterized by altered lipid metabolism, chronic low-grade inflammation, and dysfunction in several key signaling pathways, including those involving insulin, leptin, and adiponectin." (PMID 39974837, 2025). "Baseline insulin levels and c-peptide were also significantly higher in those with obesity." (PMID 40781458, 2025). "Previous studies have found that a higher BMI can be a protective factor against sarcopenia but BMI exceeding the cutoff for obesity is still one of the important factors that lead to further sarcopenia by increasing the level of pro-inflammatory factors, promoting insulin resistance." (PMID 41517409, 2025). "The positive correlation between fat intake and fasting insulin levels may represent a compensatory response to maintain glycemic stability, a phenomenon that mirrors the hyperinsulinemia observed in obesity." (PMID 41319797, 2025).